TF (transferrin)
Diseases named in the same sentence as TF in open-access papers (continued):
Sharing a sentence is not in itself a finding about the gene and the disease.
tumor (continued). "After intravenous injection, the nanoprobes bind to transferrin, enhancing tumor targeting through damaged blood vessels and thus accumulating in the tumor area." (PMID 36274142, 2022). "The transferrin-targeted NPs were proven effective carriers of TPT in vivo experiments using an MDA-MB-231 tumor xenografted mice model." (PMID 36612067, 2022). "The synthesis of transferrin exhibits an autocrine mechanism to support iron supply and tumor cell growth." (PMID 36497050, 2022). "In humans, the transferrin, TFR1 gene has been found to be up-regulated in breast cancers, and higher levels of this protein have been associated with higher tumor grades/stages, but also with a significantly worse survival." (PMID 35309358, 2022). "The impact on BP, such as regulation of DNA demethylation, transferrin transport, and pyroptosis process involved in development, indicated that these lncRNAs have potential biological functions, especially in tumor progression." (PMID 35433477, 2022). "GM-CSF secretion by malignant cells induces the production of transferrin in Ly6G+ cells from 4T1-bearing mice that, in turn significantly enhances primary tumor growth in vivo and in vitro." (PMID 35309358, 2022). "For example, galectin-3 can bind to the galactose-β1,3N-acetyl-galactosamineα-Thr/Ser, an oncofetal carbohydrate antigen (Thomsen-Friedenreich antigen, TF antigen) that occurs in >90 tumour cells and can be proteolytically removed by O-glycanase." (PMID 36291660, 2022). "Based on this active transport capability, transferrin NPs can be used for tumor diagnosis and targeted delivery of therapeutic drugs." (PMID 35860027, 2022). "TF-PEG liposomes led to 35.2 μg/g of 10B accumulated in the tumor 24 h after injection, which was 2.1-fold higher than that of bare liposomes." (PMID 36552793, 2022). "Various functional ligands including folic acid, hyaluronic acid, transferrin, peptides, and antibodies, have been extensively explored to develop tumor-selective drug delivery systems." (PMID 35762636, 2022). "For example, transferrin (Tf) is treated as a targeting ligand for tumor, or brain targeting due to the overexpress of the transferrin receptor (TfR) in cancer cells and the blood-brain barrier (BBB) endothelial cells." (PMID 36134930, 2022). "Transferrin targeting has been shown to be effective in many tumor targeting studies using nanoparticles." (PMID 35335886, 2022). "A wide body of evidence suggests that full length TF (flTF) on subendothelial cells is highly expressed in a variety of solid tumors and tumor vasculature and is a result of well-defined upstream events occurring during oncogenic transformation." (PMID 35406450, 2022). "Gallium binds transferrin and enters tumor cells via transferrin receptor 1, which results in disruption of iron metabolism." (PMID 35502218, 2022). "It is worth noting that the procoagulant potential of TF-expressing MVs derived from human tumor cell lines is reduced in PAR2−/− mice following clopidogrel treatment." (PMID 36013171, 2022). "After the first week of tumor engraftment, transferrin-targeted and rhodamine-labeled SANPs-siPraja2 were perfused in mice tail vein." (PMID 35918402, 2022). "Transferrin, an antibody-binding protein (Protein G) folic acid can be conjugated to these carriers to make them more specific to tumor cells and give the direct visualization of the tumor for diagnosis." (PMID 36012269, 2022). "Transferrin-decorated multifunctional nanoparticles (NPs) based on γ-cyclodextrin for tumor-targeted therapy were reported." (PMID 36612067, 2022). "Lastly, we generated transferrin tethered C-dot-chalcone conjugates to investigate the enhancement of chalcone therapeutic efficacy by docking them into the tumor cell via the receptor mediated endocytosis." (PMID 35890360, 2022). "Elevated levels of hepcidin are found in different tumor types, inhibiting transferrin (Tf)-mediated iron transport." (PMID 36497050, 2022).
tumor (continued). "We found that iron supplementation increases the anti-tumor effect of VC, which was influenced by the cellular iron uptake pathway–transferrin (TF)/transferrin receptor (TFR) system." (PMID 36139668, 2022). "Researchers have used proteins (antibodies and transferrin), peptides, nucleic acids, small molecules (anisamide, folate, etc.), aptamers, and polysaccharides as ligands that preferentially bind to tumor cells." (PMID 35248060, 2022). "Various functional ligands including folic acid, hyaluronic acid, transferrin, peptides, and antibodies, have been extensively examined to develop tumor-selective drug delivery systems." (PMID 35762636, 2022). "Their main advantage is their porous structure which allows inner encapsulation of drugs, but also the surface linkage of tumor-targeting peptides (e.g., folic acid, transferrin) and pH-responsive binders (e.g., imidazole, hydrazine) can prove useful too." (PMID 35448133, 2022). "We next used the transferrin-nanoparticle delivery of pSicoCD44v6 shRNA plus Fabpl-Cre to determine whether silencing the expression of CD44v6, or of CD44v6-containing variants, can inhibit the tumor cell survival and growth by reducing WNT-CD44v6-MDR1 signaling." (PMID 35982950, 2022). "In the future, nanoshell-based genetically encoded nanomaterials obtained in this study can be vectorized with specific ligands such as transferrin whose receptor is overexpressed in tumor cells." (PMID 36555233, 2022). "Depletion of neutrophils inhibited lung metastasis and transferrin production in the metastatic microenvironment, while deletion of transferrin receptors suppressed the growth of lung-colonizing tumor cells." (PMID 35664746, 2022). "Transferrin (Tf), a targeting moiety for cancer cells based on a higher expression of the Tf receptor in tumor cells, was coupled to Δ9-THC-loded PLGA NPs to modulate the interaction of the particles with the target cells." (PMID 35079042, 2022). "An important question raised by this work is what proportion of the tumor cellular iron content is free (i.e., reactive) vs. bound (i.e., inert) in ferritin or endocytosed transferrin." (PMID 35992801, 2022). "Engineered EVs with superparamagnetic-conjugated transferrin have been shown to target tumor cells and reduce tumor growth in vivo." (PMID 35453619, 2022). "Proteomic approaches elucidated the TANs secretome, identifying transferrin as the major mitogen for tumor cells." (PMID 35664746, 2022). "Transferrin (Tf) and Lf are broadly employed as tumour-targeting ligands because their receptors are excessively expressed in a variety of human carcinomas, including GBMs and the BBB." (PMID 34868634, 2021). "In conclusion, we fabricated a new nanoplatform assembled by a transferrin-based nanocomplex and thermo-sensitive liposomes for dual- targeting drug delivery, which is a potent tumor therapy strategy with good prospects." (PMID 34959271, 2021). "TFRC is involved in the uptake of the iron-transporting glycoprotein transferrin into cells and helps meet the high demands for iron in tumor cells." (PMID 33690729, 2021). "The list containing 318 TF genes was obtained from the Cistrome database, and 144 differentially expressed TFs were screened from previously obtained DEGs in normal and tumor tissues." (PMID 34109216, 2021). "The action of VEGF in neoplastic disease leads to enhanced TF expression by endothelial cells and increased release of vWF." (PMID 33146401, 2021). "This analysis showed also that CUP tissues globally displayed higher EMT TF expression as compared with agnospheres, possibly as result of contamination by tumor microenvironment cells." (PMID 33941777, 2021). "In general, transferrin can be modified to the surface of cationic liposomes via crosslinking or electrostatic adsorption to obtain transferrin-receptor-mediated tumor targeting ability." (PMID 34959271, 2021).
tumor (continued). "Platelets are indirectly activated by tumor cells via coagulation activation induced mainly by TF present on tumor cells." (PMID 33146401, 2021). "Tumor-specific ligand-like peptides, galactose-conjugated chitosan, transferrin, folic acid, and monoclonal antibodies have been employed to target microbubbles to tumor cells for the treatment of many cancers." (PMID 34259093, 2021). "Compared to the mice treated with free DiR or DiR-LTSLs, the ex vivo fluorescence signal of tumor was significantly enhanced, demonstrating the excellent transferrin-mediated tumor targeting of TMNPs." (PMID 34959271, 2021). "The superparamagnetic γ-Fe2O3 nanoparticles (NPs) were covalently grafted with GO nanosheets with tumor-targeting protein transferrin (TF) and the mitochondrion-targeting peptide (MitP)." (PMID 34068529, 2021). "The nanoscale self-assembly properties of small molecule drugs are important in tumor-targeting therapy, and drug delivery systems based on TF/TFR are important." (PMID 33892746, 2021). "The use of resveratrol-loaded polyethylene glycol-polylactic acid nanoparticles with transferrin moieties (Tf-NP-RES) reduced tumor volume and prolonged the survival in C6 orthotopic rats and U87MG-xenograft mice." (PMID 33671796, 2021). "ONC has been fused to the N-terminal domain of transferrin (TF) (rONC-TFn) in order to increase its selectivity for tumor cells and reduce its toxic side effects." (PMID 33435285, 2021). "TF expression in cancer is related with a variety of pathologic processes, such as thrombosis, metastasis, tumor angiogenesis, and tumor growth." (PMID 34107980, 2021). "The TF antigen is rarely detected in normal cells but is frequently expressed in tumor cells, with pathological and clinical consequences." (PMID 33572915, 2021). "PTX@TF killed tumor cells with higher efficiency due to the enhanced cellular uptake mediated by transferrin." (PMID 34959271, 2021). "The released PTX@TF entered cancer cells via transferrin-receptor-mediated endocytosis and inhibited the survival of tumor cells." (PMID 34959271, 2021). "TF expression in the neoplastic cells was considered positive when more than 5% of tumor cells were stained." (PMID 33572915, 2021). "This strategy exploits the fact that tumor cells overexpress transferrin while vasculature that supply blood to these newly formed tumor cells overexpress integrins." (PMID 33777893, 2021). "RGD is much better than transferrin and folate, which can only target cancer cells but cannot target the tumor neo-vasculature." (PMID 34959463, 2021). "By a proteomic approach, the iron-transporting protein transferrin was identified as the major mitogen for tumor cells that are secreted by neutrophils and the depletion of neutrophils suppressed transferrin production and lung metastasis." (PMID 33418996, 2021). "Because TFR is overexpressed in a variety of tumor cells, TF/TFR-mediated cell events have been used to deliver therapeutic drugs to malignant tumor cells (Tros de Ilarduya and Düzgüneş, 2013)." (PMID 35082668, 2021). "Because tumor tissues have more TFRs than normal tissues, 2b can target tumor tissues with TF as the vector." (PMID 33892746, 2021). "Regarding TNM staging, a significant statistical association between TF expression and T staging was found (p = 0.02), with higher TF expression in tumor progression (7% in pT1, 26% in pT2, and 51% in pT3)." (PMID 33572915, 2021). "Loaded with special markers on the cancer cell surface, such as transferrin, growth factors, peptides, folate, antibodies, or antibody fragments, nanozyme systems not only recognize tumor more sensitively, but also result in drug delivery more specifically." (PMID 34737942, 2021). "Another issue is the phenomena of in vivo transmetallation or transchelation of 89Zr with metal complexing proteins such as transferrin and ceruloplasmin in the liver and kidneys which also increases off-tumor irradiation." (PMID 34621145, 2021).
tumor (continued). "Our data also provide new interconnections between tumor-intrinsic iron metabolism and suppressive tumor immune microenvironment through the TF/TFRC axis." (PMID 34389031, 2021). "According to recent studies, the oncogenic events in cancer cells (such as the expression of mutant K-ras, EGFR) lead to the increased TF levels and activity, which thereby promoting tumor aggressiveness, angiogenesis, and hypercoagulability." (PMID 33243184, 2020). "The retention of artesunate concentration in the tumor was 131.06 μg/g when compared to the free drug which was 11.13 μg/g indicating that the transferrin enhanced the drug accumulation into the tumor." (PMID 32784933, 2020). "The clinical characteristics and whole TF expression profile (FPKM normalization) of 370 tumor samples were acquired for survival analyses." (PMID 32117710, 2020). "GM-CSF produced primarily by tumor cells induces transferrin synthesis in neutrophils through the Janus kinase (Jak)-Stat5β pathway." (PMID 33101283, 2020). "It has been reported that Gal-3 exerts its pro-tumor promoting properties through the Thomsen–Friedenreich (TF) antigen, which occurs in 90% of all human cancer cells." (PMID 32486344, 2020). "In non-ovarian tumor cell types, the binding of Gal-3 to cancer associated TF/MUC1 induces redistribution of MUC1 on the cell surface, increasing cancer cell homotypic aggregation and the formation of tumor micro-emboli." (PMID 32486344, 2020). "GM-CSF, derived mainly from metastatic tumor cells, selectively induces transferrin gene expression in neutrophils through the Jak/Stat5β pathway." (PMID 33679721, 2020). "The NPs were conjugated with apo‐transferrin (Tf) for tumor targeting, while additional conjugation of titanocene (Tc), a photoinitiator in the metallocene family, enhanced and complemented the cytotoxicity of TiO2." (PMID 33344143, 2020). "By employing a proteomic/functional approach, we unexpectedly identified transferrin as the major mitogen for tumor cells secreted by neutrophils." (PMID 33679721, 2020). "Capturing CTCs with a materials platform using transferrin (Tf) as a capture ligand have been studied widely due to higher concentration of Tf receptor in tumor cells compared to healthy cells." (PMID 32561829, 2020). "In TCGA‐STAD cohort, we selected all 27 paired tissues (tumor and normal tissue) as an expression profile to conduct different expressed analysis for each TF gene." (PMID 32463580, 2020). "The decoration of transferrin on the GO nanoparticle enhanced the targeting efficacy of the nanoparticle to the tumor cells with overexpressed transferrin receptor thereby increasing iron ion that interacts with dihydroartemisinin." (PMID 32784933, 2020). "By analyzing the secretome of neutrophils isolated from tumor-bearing mice, the iron-transporting protein transferrin secreted by Ly6G+ neutrophils was identified as the major mitogen for tumor cells." (PMID 33101283, 2020). "Meanwhile, the hub genes from the DEGs between T and LM groups (ALB, FGG, AHSG, TF, and GC) also showed marked alterations in the correlations, indicating potential mechanisms involved in the tumor metastasis." (PMID 32496505, 2020). "Transferrin and dihydroartemisinin were modified on the surface of graphene oxide (GO) nanoparticles for tumor therapy." (PMID 32784933, 2020). "Using intratumoral as well as intravenous application of NDA135b targeted with transferrin led to accumulation of NDA135b in the excised tumor mass and significant downregulation of cytoplasmic microRNA-135b." (PMID 31181619, 2019). "The combination of active targeting transferrin, with the passive accumulation of liposomes in tumours due to the enhanced permeability and retention effect, should provide tumour‐selective targeting of the plumbagin‐loaded liposomes to the cancer cells." (PMID 31341642, 2019).
tumor (continued). "In order to evaluate percentage of 4T1 cells and MF interacting with NDA135b within the tumor microenvironment, we incubated co-cultures with NDA135b and subsequently detected cells positive for transferrin." (PMID 31181619, 2019). "Taken together, Trousseau’s syndrome is well recognized as thrombotic disorders that are not only due to cancer-derived mucin or TF, but also to other thrombogenic mechanisms, such as tumor hypoxia and MET gene activation." (PMID 30959839, 2019). "It has been shown that the cellular uptake of transferrin by tumors in rats is correlated with the proliferation activity of the tumor cells (i.e., the faster the tumor growth, the higher is the uptake of transferrin)." (PMID 30943985, 2019). "The transferrin and anti-nestin antibody carrying system was shown to have a favorable pharmacokinetic profile and was effective in the reduction of the tumor volume in comparison to the treatment with TMZ." (PMID 30791358, 2019). "Granulocyte-macrophage colony-stimulating factor (GM-CSF), which is produced primarily by tumor cells, is a selective inducer of de novo transferrin synthesis in neutrophils through the Jak/Stat5β pathway." (PMID 31130637, 2019). "The minority of meta-modules related to pro-tumor activity as Tumor Growth, Immunosuppressive Core Pathways, Immunosuppressive MiRNA and TF correlated negatively with patient survival." (PMID 31641119, 2019). "Nanodiamonds within NDA135b were decorated with transferrin in order to facilitate their uptake by tumor cells." (PMID 31181619, 2019). "In this study, we propose a novel approach based on transferrin (Tf)-conjugated poly(lactide-co-glycolide) (PLGA) nanoparticles loaded with docetaxel trihydrate (DCT) for tumor targeting." (PMID 31752417, 2019). "Here, detection of NDA135b in tumor samples was enabled by using transferrin–Alexa Fluor 488 conjugate adsorbed on the nanodiamond core." (PMID 31181619, 2019). "TF and FA are very commonly used malignant tumor-targeting ligands, as most tumor cells express high levels of TfR or FR on their surface, while the expression of TfR and FR in normal tissues are much lower." (PMID 31915707, 2019). "Further, MBP-426 (Mebiopharm), a liposome loaded with oxaliplatin (L-OHP), was conjugated to transferrin (Tf) for tumor targeting and currently undergoing phase II trials." (PMID 30905189, 2019). "We expected the tumor cell will uptake most of NDA135b due to specific targeting of NDA135b with transferrin and shielding of the complex from macrophages." (PMID 31181619, 2019). "The results of these tests confirm the validity of our use of transferrin as a driving factor, since its expression depends on the tumor environment." (PMID 31835393, 2019). "In vivo, the intravenous injection of transferrin‐bearing liposomes entrapping plumbagin led to tumour suppression for 10% of B16‐F10 tumours and tumour regression for a further 10% of the tumours." (PMID 31341642, 2019). "Recent studies indicate that depletion of neutrophils inhibited lung metastasis, and the iron-transporting protein transferrin was identified as the major mitogen for tumor cells secreted by neutrophils." (PMID 31130637, 2019). "Study shows that Jacalin displays strong affinity for Galβ1–3GalNAc, the Thomsen–Friedenreich (TF) antigen so as to perform function of recognition, differentiation and anti-proliferation of tumor cells." (PMID 29661177, 2018). "As a promising tumor targeting ligand, transferrin is frequently adopted to facilitate targeting delivery of theranostics." (PMID 29755355, 2018). "In accordance to local hyperthermia, whole body hyperthermia after repeated injection of transferrin also resulted tumor-selective temperature elevation." (PMID 30202000, 2018).